CLPTM1 (CLPTM1 regulator of GABA type A receptor forward trafficking)
Description:
Involved in GABAergic but not glutamatergic transmission. Binds and traps GABAA receptors in the endoplasmic reticulum (ER). Modulates postsynaptic GABAergic transmission, and therefore inhibitory neurotransmission, by reducing the plasma membrane expression of these receptors. Altered GABAergic signaling is one among many causes of cleft palate (By similarity). Might function as a lipid scramblase, translocating lipids in membranes from one leaflet to the other one (By similarity). Required for efficient glycosylphosphatidylinositol (GPI) inositol deacylation in the ER, which is a crucial step to switch GPI-anchored proteins (GPI-APs) from protein folding to transport states. May play a role in T-cell development (By similarity).
Tractability: Antibody: its Gene Ontology location is reachable by antibodies, with high confidence; UniProt predicts a signal peptide or a membrane-spanning region. PROTAC: ubiquitination databases record sites on it; its protein half-life has been measured.
Gene: Protein-coding gene on chromosome 19 (44,954,585 to 44,993,341, forward strand). Ensembl gene ENSG00000104853.
Subcellular location: Membrane
Subcellular location (Human Protein Atlas): Endoplasmic reticulum
Gene Ontology:
Molecular function: protein binding; GABA receptor binding
Biological process: regulation of T cell differentiation in thymus
Cellular component: membrane; endomembrane system; external side of plasma membrane; plasma membrane
Genetic constraint (gnomAD): Loss-of-function variants: 21 observed, 75.25 expected, observed/expected ratio (o/e) 0.28, 90% interval 0.2 to 0.4. The upper end of that interval is the gene's LOEUF score, 0.4, which puts it in group 1 of 6, group 1 being the genes least tolerant of losing a copy. Missense variants: 630 observed, 924.32 expected, observed/expected ratio (o/e) 0.68, 90% interval 0.64 to 0.73. Synonymous variants: 371 observed, 384.25 expected, observed/expected ratio (o/e) 0.97, 90% interval 0.89 to 1.05.
Homologues: Orthologues: chimpanzee CLPTM1 (99% identical), macaque CLPTM1 (97% identical), dog CLPTM1 (97% identical), mouse Clptm1 (94% identical), guinea pig CLPTM1 (94% identical), rat Clptm1 (92% identical), rabbit CLPTM1 (90% identical), pig CLPTM1 (87% identical), tropical clawed frog clptm1 (77% identical), zebrafish clptm1 (74% identical), Drosophila melanogaster CG3702 (50% identical), Caenorhabditis elegans C36B7.6 (48% identical), and 1 more. Paralogues in human: CLPTM1L (29% identical).
Diseases named in the same sentence as CLPTM1 in open-access papers:
CLPTM1 is named in the same sentence as 20 diseases in open-access papers, as found by Europe PMC text mining. Sharing a sentence is not in itself a finding about the gene and the disease. The quoted sentences say what the papers report.
lung carcinoma (4 papers, 2013 to 2024). "CEACAM19 gene located in chromosome 19, a previous study showed high expression of CEACAM19 for patients with breast cancer; CLPTM1 has been shown to increase the risk of lung cancer and melanoma." (PMID 30666269, 2018). "According to a GWAS, the SNP rs2736100 localizes to CLPTM1 L-TERT and is linked to the risk of lung cancer." (PMID 35479964, 2022). "Moreover, whether the expression level of CLPTM1 influences the disease-free survival (DFS) and overall survival (OS) of lung cancer was investigated." (PMID 39113849, 2024).
Alzheimer disease (3 papers, 2020 to 2024). A progressive, neurodegenerative disease characterized by loss of function and death of nerve cells in several areas of the brain leading to loss of cognitive function such as memory and language. "The associations between CLPTM1 gene variants and expression and Alzheimer disease have been observed in genome-wide and transcriptome-wide association studies." (PMID 36011277, 2022).
breast carcinoma (2 papers, 2008 to 2018). "In women with breast cancer submitted to neoadjuvant chemotherapy based in doxorubicin, tumor expression of groups of three genes (PRSS11, MTSS1, CLPTM1 and PRSS11, MTSS1, SMYD2) have classified them as responsive or resistant." (PMID 18601734, 2008).
breast tumors (1 paper, 2012). "Interestingly, the homologue CLPTM1 has been found to be expressed at higher levels in doxorubicin resistant breast tumors, and expression of CLPTM1 is predictive of response to doxorubicin." (PMID 22675468, 2012).
cognitive deficits (1 paper, 2025). "Subsequent in vivo studies found that Clptm1 knock-out (KO) mice had elevated phasic and tonic inhibitory transmission and associated cognitive deficits, and the downregulation of Clptm1 expression protected against pentylenetetrazol-induced epilepsy in rat." (PMID 40112516, 2025).
epilepsy (1 paper, 2025). A brain disorder characterized by episodes of abnormally increased neuronal discharge resulting in transient episodes of sensory or motor neurological dysfunction, or psychic dysfunction. "However, de novo Clptm1 variants are associated with epilepsy and shown to reduce surface expression of the GABAAR γ2 subunit and GABAAR current response under voltage clamp." (PMID 40112516, 2025).
infection (1 paper, 2018). The state of being infected such as from the introduction of a foreign agent such as serum, vaccine, antigenic substance or organism. "In contrast, depletion of two other identified proteins, adipocyte plasma membrane-associated protein (APMAP) and cleft lip and palate transmembrane protein 1 (CLPTM1), led to an increase of infection by over 70%, indicating that these factors restrict viral entry under physiological conditions." (PMID 29666374, 2018).
psychiatric disorder (1 paper, 2025). A disorder characterized by behavioral and/or psychological abnormalities, often accompanied by physical symptoms. "Twelve lead SNPs were located within 10 genes (BIN1, TMEM106B, AP001257.1, PICALM, SLC24A4, PVRL2, APOE, CLPTM1, CTB-179K24.3, and CASS4) for AD, and all three stress-related psychiatric disorders were identified using FUMA." (PMID 39975850, 2025).
Tumor (1 paper, 2008). "Relative gene expression was evaluated and tumor samples were then spatially distributed according to the expression of the trios of genes: PRSS11, MTSS1, CLPTM1 and PRSS11, MTSS1, SMYD2." (PMID 18601734, 2008). "Expression of PRSS11, MTSS1, CLPTM1 and SMYD2 was determined in tumor samples." (PMID 18601734, 2008). "Tumor expression of PRSS11, MTSS1, CLPTM1 and SMYD2, was evaluated by real time PCR." (PMID 18601734, 2008).
CLPTM1 also shares sentences with these, for which no sentence is quoted: age-related macular degeneration (1 paper); behavioral disorders (1); cleft lip palate (1); cognitive decline (1); dyslipidemia (1); Hyperglycemia (1); melanoma (1); Obesity (1); orofacial cleft (1); ovarian tumor (1); type 2 diabetes (1).